SGSM2 (small G protein signaling modulator 2)
Description:
Possesses GTPase activator activity towards RAB32, RAB33B and RAB38. Regulates the trafficking of melanogenic enzymes TYR, TYRP1 and DCT/TYRP2 to melanosomes in melanocytes by inactivating RAB32 and RAB38. Inhibits RAB32 and RAB38 activation both directly by promoting their GTPase activity and indirectly by disrupting the RAB9A-HPS4 interaction which is required for RAB32/38 activation.
Synonyms: KIAA0397; RUTBC1
Tractability: PROTAC: ubiquitination databases record sites on it; its protein half-life has been measured.
Gene: Protein-coding gene on chromosome 17 (2,337,492 to 2,381,058, forward strand). Ensembl gene ENSG00000141258.
Subcellular location: Cytoplasm; Melanosome
Subcellular location (Human Protein Atlas): Cytosol; Nucleoplasm
Gene Ontology:
Molecular function: GTPase activator activity; small GTPase binding
Biological process: late endosome to Golgi transport
Cellular component: cytoplasm; melanosome; cytoplasmic vesicle
Genetic constraint (gnomAD): Loss-of-function variants: 86 observed, 120.97 expected, observed/expected ratio (o/e) 0.71, 90% interval 0.6 to 0.85. The upper end of that interval is the gene's LOEUF score, 0.85, which puts it in group 3 of 6, group 1 being the genes least tolerant of losing a copy. Missense variants: 1,373 observed, 1,389.8 expected, observed/expected ratio (o/e) 0.99, 90% interval 0.94 to 1.03. Synonymous variants: 597 observed, 563.7 expected, observed/expected ratio (o/e) 1.06, 90% interval 0.99 to 1.13.
Homologues: Orthologues: chimpanzee SGSM2 (99% identical), macaque SGSM2 (95% identical), rabbit SGSM2 (93% identical), rat Sgsm2 (93% identical), mouse Sgsm2 (93% identical), guinea pig SGSM2 (92% identical), pig SGSM2 (92% identical), dog SGSM2 (87% identical), tropical clawed frog sgsm2 (76% identical), zebrafish sgsm2 (72% identical). Paralogues in human: SGSM1 (60% identical), TBC1D9 (11% identical), TBC1D9B (11% identical), TBC1D8 (11% identical), TBC1D30 (10% identical), TBC1D8B (9% identical), EVI5L (9% identical), TBC1D4 (9% identical), EVI5 (9% identical), RABGAP1 (8% identical), TBC1D1 (8% identical), TBC1D2 (8% identical), and 33 more.
Diseases named in the same sentence as SGSM2 in open-access papers:
SGSM2 is named in the same sentence as 18 diseases in open-access papers, as found by Europe PMC text mining. Sharing a sentence is not in itself a finding about the gene and the disease. The quoted sentences say what the papers report.
breast carcinoma (3 papers, 2019 to 2024). "SGSM2 downregulation promoted estrogen receptor‐positive breast cancer cell migration via modulating cell adhesion and cytoskeleton dynamics." (PMID 33386701, 2021). "These two results appear contradictory; thus, we analysed the possible effect of SGSM2 gene expression in BC patients in the TCGA Breast Cancer (BRCA) cohort." (PMID 30744493, 2019). "A study relating Sgsm2 with breast cancer showed that silencing the expression of Sgsm2 protein resulted in a decreased expression of epithelial markers such as E-cadherin, β-catenin, and Paxillin, in addition to increased expression of markers such as Snail and Twist-1." (PMID 39895822, 2024). "Next, we treated a panel of adherent breast cancer cell lines and a human melanoma cell line (MDA-MB-435 s) with or without 21 μM trypsin-EDTA and analysed SGSM2 protein by western blot." (PMID 30744493, 2019).
benign breast tumour (1 paper, 2019). "In addition, fibroadenoma is a benign breast tumour with proliferation of both epithelial and stromal components, and TCGA data showed higher SGSM2 gene expression in normal breast tissues than in breast tumour tissues." (PMID 30744493, 2019).
breast tumours (1 paper, 2019). "Because BC is a heterogeneous disease that is caused by DNA mutations or epigenetic changes, we conjectured that these phenomena could disrupt the connection between SGSM2 and other genes in breast tumours, especially the ERBB2 gene." (PMID 30744493, 2019). "Moreover, SGSM2 protein was highly expressed in ER-positive BC cells (BT474, MCF-7, T-47D, and ZR-75) and in ER-positive breast tumour tissues." (PMID 30744493, 2019).
colorectal cancer (1 paper, 2021). A primary or metastatic malignant neoplasm that affects the colon or rectum. "DSVs in SGSM2 and LHFPL3 were relevant to colorectal cancer, whereas ADAP1, DLGAP2, ERC1, and PPP6R2 were related to gynecologic cancer." (PMID 33431054, 2021).
Fibroadenoma (1 paper, 2019). A benign tumor of the breast characterized by the presence of stromal and epithelial elements. "However, we observed that one common characteristic of SGSM2 and CDH1 is that both are highly expressed in fibroadenoma (*P = 0.002 and D, *P = 0.038)." (PMID 30744493, 2019).
infiltrating ductal carcinoma (1 paper, 2019). "Unexpectedly, SGSM2 mRNA levels showed a higher distribution in invasive lobular carcinoma (ILC) than in infiltrating ductal carcinoma (IDC) (***P < 0.001)." (PMID 30744493, 2019).
Obesity (1 paper, 2018). Accumulation of substantial excess body fat. "Instead, our screen suggests that different nearby cis gene may be more fruitful for further functional follow up for obesity, namely ZCCHC8, VPS33A, RSRC2; SPDEF, NUDT3; SETD1, VKORC1; SGSM2, SRR; VASP, SIX5; OTX1; BANK1; ARIH1; ELL; CHST8, respectively." (PMID 29608557, 2018).
renal fibrosis (1 paper, 2024). A final common manifestation of a wide variety of chronic kidney diseases characterized by glomerulosclerosis and tubulointerstitial fibrosis. "Sgsm2 has great potential to act as a regulator of the epithelial–mesenchymal transition process in renal fibrosis by decreasing the expression of epithelial markers and increasing the expression of mesenchymal proteins." (PMID 39895822, 2024). "Although the relationship between Sgsm2 and kidney disease has not been described in the literature, this protein may be related to the EMT that occurs in renal fibrosis in patients with CKD." (PMID 39895822, 2024).
thyroid (1 paper, 2022). "The aim of this study was to explore the functions and underlying molecular mechanism of SGSM2 in the progression of thyroid tumorigenesis." (PMID 35264562, 2022).
cancer (2 papers, 2019 to 2024). A tumor composed of atypical neoplastic, often pleomorphic cells that invade other tissues. "Although there are few studies indicating an inhibitory effect of calebin A on cancer metastasis, we here verified its ability to suppress cancer cell adhesion, and this activity might be associated with SGSM2 protein expression." (PMID 30744493, 2019). "These evidences suggest that SGSM2 plays a role in modulating cell adhesion and cytoskeleton dynamics during cancer migration." (PMID 30744493, 2019). "Our study verified that inhibition of SGSM2 could reduce cell adhesion and increase cancer cell migration; however, we also found that SGSM2 was involved in modulating E2-induced cell motility." (PMID 30744493, 2019). "Herein, we demonstrated that SGSM2 is involved in EGF-induced E-cadherin endocytosis and is associated with E2-induced cancer cell migration, and SGSM2 might be involved in regulation of cytoskeleton dynamics." (PMID 30744493, 2019). "These novel findings demonstrate that SGSM2 may be involved in the modulation of cell adhesion and cytoskeleton dynamics through an E-cadherin-mediated EMT process during the initial stage of cancer migration." (PMID 30744493, 2019). "SGSM2 downregulation enhanced the phosphorylation of focal adhesion kinase (FAK; Y576/577), decreased the expression of epithelial markers such as E-cadherin, β-catenin, and Paxillin, and increased the expression of Snail and Twist-1, which reduced cell adhesion and promoted cancer cell migration." (PMID 30744493, 2019). "Although calebin A decreased SGSM2 protein levels and inhibited NNK-induced cell adhesion, these findings do not demonstrate that SGSM2 is involved in regulating cancer cell adhesion." (PMID 30744493, 2019).
tumor (2 papers, 2019 to 2022). "Collectively, based on our analysis, SGSM2 functions as a tumor suppressive gene in TC harboring the wild type RAS." (PMID 35264562, 2022). "Based on these results, SGSM2 serves as a tumor suppresser in RASWT TC cells via suppression of the MAPK/ERK and PI3K/AKT network activities." (PMID 35264562, 2022). "In general, our data demonstrates the tumor suppressive activity of SGSM2 in RASWT TCs, and provides an excellent prognostic and therapeutic candidate for this type of TC." (PMID 35264562, 2022). "Compared with SGSM3 expression, SGSM2 expression in tumours was significantly higher, and its percentage of occurrence in the T > N group was 74%." (PMID 30744493, 2019). "In summary, the present study reports a tumor suppressive role of SGSM2 in TC." (PMID 35264562, 2022). "In summary, SGSM2 is decreased and serves a tumor suppressive role in RASWTTC cells." (PMID 35264562, 2022). "Collectively, these results indicate that SGSM2 serves a tumor suppressive role in TC." (PMID 35264562, 2022). "Based on quantitative real-time PCR, SGSM2 gene expression in paired tumour tissues was 2-fold higher than that in paired normal tissues from 200 BC patients, and this expression significantly correlated with luminal A type BC rather than the HER2-positive or TNBC types." (PMID 30744493, 2019). "Therefore, SGSM2 might be a mediator to maintain the equilibrium of cell motility and might play a tumour suppressor role during BC formation initiation." (PMID 30744493, 2019). "We further investigated SGSM2 and SGSM3 mRNA levels in tumours and paired normal tissues from 53 BC patients via RT-PCR." (PMID 30744493, 2019). "We revealed that SGSM2 overexpression limited xenograft tumor growth driven by 8305 C, while no influence was observed in tumors driven by CAL-62." (PMID 35264562, 2022). "EGF has been reported to induce focal adhesion disassembly and enhance tumour cell motility through EGFR-activated E-cadherin endocytosis, and SGSM2 has been reported to interact with RAB family proteins, who function in recycling of vacuoles between the early endosome and plasma membrane." (PMID 30744493, 2019). "Among 53 BC patients, 74% had SGSM2 mRNA expression in tumours that was higher than that in normal tissue (T > N, n = 39), but in 26% of patients, SGSM2 mRNA expression in tumour tissue was less than that in normal tissue (N > T, n = 14)." (PMID 30744493, 2019). "According to our first screening, SGSM1 mRNA was not expressed in BC or breast epithelial cells, and compared with SGSM2 expression, SGSM3 expression was not different between normal breast tissue and tumour tissues based on RT-PCR." (PMID 30744493, 2019).
SGSM2 also shares sentences with these, for which no sentence is quoted: gynecologic cancer (1 paper); invasive lobular carcinoma (1); kidney disease (1); melanoma (1); skin cutaneous melanoma (1); thyroid cancer (1); type 2 diabetes mellitus (1).